PTX3 (pentraxin 3)
Diseases named in the same sentence as PTX3 in open-access papers (continued):
Sharing a sentence is not in itself a finding about the gene and the disease.
COVID-19 (continued). "Pentraxin-3, for example, is expressed by lung macrophages and endothelial cells from COVID-19 patients, and its level in plasma acts as a strong prognostic marker for 28-day mortality." (PMID 39555923, 2024). "Induction of serum PTX3 was mainly found 1 day after the COVID-19 vaccine in FlubeforeCoV (d30 + 1) and increased in HS of the FluplusCoV cohort." (PMID 39340080, 2024). "It has been well known that circulating increasing PTX3 levels are considered as an independent prognostic indicator in inflammatory diseases including COVID-19 and neuroinflammation." (PMID 39666228, 2024). "IL-8, D-dimer, S100B, IL-6, Angpt-2, MMP-8, TNF-R1, u-PAR, u-PA, osteopontin, IL-13, TNF-α, pentraxin-3, P-selectin, fractalkine, and SP-D levels were elevated in critically ill COVID-19 males compared to severe cases." (PMID 39507250, 2024). "Concerning this, previous research has shown that PTX3 levels are a reliable indicator of death in COVID-19 patients." (PMID 37762499, 2023). "Other studies have demonstrated the involvement of PTX3 in the immunopathology of some diseases, such as severe forms of COVID-19 and chronic hepatitis C." (PMID 38053036, 2023). "Analyzing PTX3 and related panels of inflammatory proteins, inflammatory overload appears to be consistent in both previously COVID-19-positive men and women, resulting statically more significant in the male population." (PMID 37762499, 2023). "High levels of PTX3 were found to be positively correlated with coagulopathies in COVID-19 patients." (PMID 37408184, 2023). "Because of inflammation, the long pentraxin PTX3 was upregulated in COVID-19 patients in general, but much more pronounced in severe COVID-19 patients." (PMID 36851312, 2023). "The accurate evaluations of PTX3 levels in COVID-19 patients can be useful in providing a new perspective for clinical practice and follow-up." (PMID 36834949, 2023). "Considering this, future studies will be able to better validate these preliminary findings, thus providing a more robust characterization regarding the immunomodulatory role of PTX3 and its driven signaling pathways in different COVID-19 clinical pictures." (PMID 37762499, 2023). "This evidence was also validated by a direct comparison of COVID-19 subjects, in which the male component showed significantly higher serum levels of PTX3 than females." (PMID 37762499, 2023). "Taken together, the data discussed in this systematic review and examined in the meta-analysis highlight PTX3 as a reliable biomarker in predicting COVID-19-related death." (PMID 36834949, 2023). "We have shown elevated levels of PTX3 and other inflammatory proteins in previously infected COVID-19-positive subjects (p < 0.001)." (PMID 37762499, 2023). "PTX3 also served as a potent independent prognostic predictor of short-term mortality during COVID-19." (PMID 37408184, 2023). "In conclusion, the collected evidence supported the development of PTX3-targeting drug therapies as a promising approach to moderate the inflammatory response in COVID-19 patients." (PMID 36834949, 2023). "As far as we know, this is the first study relating PTX3 with gender differences in the COVID-19 clinical picture." (PMID 37762499, 2023). "In COVID-19 patients, PTX3 has been extensively studied since the beginning of the pandemic, and it was found to be at higher levels during the disease compared with healthy controls." (PMID 37408184, 2023). "Our study investigated the use of PTX3 as a potential marker of COVID-19 severity and compared its performance in detecting a more severe form of the disease with that of routine laboratory parameters." (PMID 35464745, 2022). "Circulating and lung myelomonocytic cells and endothelial cells have been reported as major sources of the pentraxin long pentraxin 3 (PTX3) in COVID-19." (PMID 36289785, 2022).
COVID-19 (continued). "For all these reasons, and keeping in mind that overinflammation is among the main features of the most severe COVID-19 cases, PTX3 quantification can be an ideal candidate biomarker to identify patients at higher risk of a severe disease." (PMID 35464745, 2022). "Levels of PTX3 were measured in 152 patients hospitalized with COVID-19 at San Gerardo Hospital (Monza, Italy) since March 2020." (PMID 36389697, 2022). "Pentraxin 3 (PTX3), a potential biomarker of the severity and mortality of COVID-19 patients, is aberrantly expressed in human tumors." (PMID 36139597, 2022). "An Italian cohort study on 96 patients hospitalized for acute COVID-19 was the first to investigate the prognostic value of PTX3 in this setting." (PMID 35326373, 2022). "In a cohort of 96 patients with COVID-19, PTX3 levels measured at hospital admission were significantly increased compared to healthy controls and were predictors of 28-days mortality." (PMID 36389697, 2022). "For example, a recent study has reported that long pentraxin 3 (PTX3) is an independent strong prognostic indicator for predicting mortality in COVID-19 and is a superior biomarker compared to conventional inflammatory markers." (PMID 34943875, 2021). "PTX3, a protein we and others have previously highlighted as a prognostic marker in ICU patients with sepsis, also positively associated with COVID-19 mortality in our ICU cohort when measured by ELISA." (PMID 34099652, 2021). "PTX3 concentration was higher in COVID-19 patients with higher HOMA-IR values than those with lower HOMA-IR values." (PMID 34680053, 2021). "In animal studies, the administration of recombinant PTX-3 against various non-COVID-19 infectious agents has been shown as a full protective or adjunctive therapeutic feature from acute lung injury." (PMID 33315349, 2021). "RNA-sequencing analysis of peripheral blood mononuclear cells, single-cell bioinformatics analysis and immunohistochemistry of lung autopsy samples revealed that myelomonocytic cells and endothelial cells express high levels of PTX3 in patients with COVID-19." (PMID 34000622, 2021). "PTX3 levels are raised in adult COVID-19 patients with plasma levels serving as a strong prognostic indicator of mortality." (PMID 34632327, 2021). "While anti-SARS-CoV-2 antibody levels were similar in COVID-19 ICU patients who survived and died, MBL2 and PTX3 were associated with poor outcome pointing towards the importance of antibody-independent mechanisms of complement activation in COVID-19." (PMID 34099652, 2021). "Notably, in the context of COVID-19, PTX3 has emerged as a strong predictor of short-term mortality, outperforming conventional markers." (PMID 39878524, 2025). "A prospective cohort study also confirmed that plasma PTX3 effectively predicts the risk of respiratory failure and death within 30 days for COVID-19 patients, regardless of treatment with remdesivir or dexamethasone." (PMID 40313930, 2025). "Furthermore, a higher proportion of patients with severe COVID-19 exhibited PTX-3 levels above 5000 pg/ml even 10 months post-infection, compared to those with mild disease." (PMID 41103408, 2025). "PTX-3 may thus serve both as a biomarker for tissue damage and/or long-term immune activation and eventually post-COVID-19 complications." (PMID 41103408, 2025). "Hence, alongside PTX3, measuring sMR levels would be of added value in monitoring COVID-19 disease course." (PMID 39027374, 2024). "As the expression of soluble receptors (sCD25, sRAGE, sTNFR I/II, PTX3) can also be found in patients with bacterial sepsis, our findings and those of others support the notion that pathologies in COVID-19-induced viral sepsis and bacterial sepsis share a similar mechanistic origin." (PMID 36851312, 2023).
COVID-19 (continued). "Otherwise, our study indicated PTX3 as a credible inflammatory marker even in a follow-up of more than one month after infection, thus opening a new perspective on the validity of this protein in the context of COVID-19-related systemic inflammation." (PMID 37762499, 2023). "Furthermore, we support the development of PTX3-targeting drug therapies as a promising approach to moderate inflammatory response in COVID-19 patients or other clinical settings." (PMID 37762499, 2023). "Therefore, from this perspective, this study aimed to provide new insights into the pathophysiology of COVID-19-related systemic inflammatory response (SIR) while exploring PTX3-driven inflammatory response in the COVID-19 clinical setting." (PMID 37762499, 2023). "By univariate and multivariate logistic regression analysis, the results also demonstrated that PTX3 was the only significant proteomic predictor of ICU-related COVID-19 stay necessity among the diseased individuals after controlling their pre-existing comorbidities." (PMID 37408184, 2023). "Additionally, PTX3 serum levels significantly predicted 30-day COVID-19 patients’ respiratory failure and their respective mortality risks." (PMID 37408184, 2023). "We included 12 clinical studies evaluating PTX3 in COVID-19 patients." (PMID 36834949, 2023). "PTX3 was higher in those COVID-19 patients that possessed higher HOMA-IR values." (PMID 37408184, 2023). "Thus, considering the possible role of PTX3 in the immunopathology of SIR forms related to COVID-19, we investigated its influence on the inflammatory course in confirmed SARS-CoV-2 positive health workers compared to never-infected individuals." (PMID 37762499, 2023). "Overall, our results may support the validity of PTX3 as a systemic biomarker in prolonged systemic inflammatory responses in the context of COVID-19." (PMID 37762499, 2023). "Moreover, VEGF, as well as other angiogenic-related analytes, were found to be increased in COVID-19 patients (including PTX3), which correlated with disease severity." (PMID 36992454, 2023). "Presumably, PTX3 may be at a crossroad between COVID-19 and cancer, providing novel therapeutic opportunities for cancer patients with COVID-19." (PMID 36139597, 2022). "Recently, PTX3 was identified as a predictor of 28-day mortality of hospitalized COVID-19 patients, with increased PTX3 hypothesized to reflect the failure to regulate uncontrolled inflammation." (PMID 35991542, 2022). "In this scenario we decided to further analyse the prognostic value of PTX3 in a larger cohort of patients hospitalized with COVID-19 with the aim to extend the observations to a randomly selected population from an observational cohort, increasing its representativeness." (PMID 36389697, 2022). "If confirmed, our findings, together with previous reports, suggest that PTX3 could be the most reliable single laboratory marker currently available to assess patients with COVID-19." (PMID 36389697, 2022). "In COVID-19, PTX3 has been proposed as a biomarker able to predict mortality at 28 days." (PMID 36287942, 2022). "Therefore, our study evaluated the use of PTX3 blood concentration as a potential marker of COVID-19 severity and compared its performance with those of CRP and of other routinely determined laboratory inflammation markers." (PMID 35464745, 2022). "Whatever the mechanism, PTX3 merits further evaluation as possible marker of redundant inflammation during COVID-19, to identify patients who could benefit from immunomodulant or immunosuppressive therapy." (PMID 36389697, 2022). "PTX3 plasma level could help to identify severer patients on admission and might serve as an independent prognostic predictor of short-term mortality in COVID-19." (PMID 36139597, 2022).
COVID-19 (continued). "Moreover, in TNF-α activated monocytes, ITF3756 reduces the expression of additional biomarkers of severe COVID-19, such as PTX3, ICAM-1, S100A12, PD-L1 and MMP9, further supporting a potential role for this molecule in the treatment of the disease." (PMID 35592335, 2022). "A correlation was also observed with pentraxin-3 (PTX-3, 134 paired observations, Spearman correlation 0.62 [95%CI: 0.49; 0.72]) (p-value <0.0001), which was described as another biomarker of COVID-19 severity." (PMID 35644124, 2022). "However, even though patients were significantly older than controls (64 vs 39 years, P < 0.001), PTX3 in COVID-19 patients was higher in respect to controls (median value 31.32 vs 2.30 ng/mL, P < 0.001)." (PMID 35464745, 2022). "We hypothesize that PTX3 plasma level, as single markers or included in scores specifically designed for patients COVID-19, may be extremely useful for their prognostic stratification." (PMID 36389697, 2022). "In non-COVID-19 prospective controlled study conducted on 142 septic, septic shock and healthy individuals revealed that both the initial and follow-up PTX3 levels were consistently significantly higher in patients who died than in those who recovered (initial P = 0.004; follow-up P < 0.001)." (PMID 33315349, 2021). "Moreover, in multivariable analysis, PTX3 emerged as a strong independent predictor, better than conventional markers of inflammation, of 28-day mortality in hospitalized COVID-19 patients." (PMID 34680053, 2021). "The purpose of this study is to evaluate serum PTX-3 levels in COVID-19 patients and to investigate whether PTX-3 determines the disease prognosis." (PMID 33315349, 2021). "Upregulated PTX3 may also predict COVID-19 severity because COVID-19 patients with significantly elevated PTX3 concentrations more frequently required ICU care." (PMID 34680053, 2021). "Increased concentrations of PTX3 in COVID-19 patients may reflect failed negative regulation of uncontrolled inflammation—cytokine storm." (PMID 34680053, 2021). "Moreover, other studies emphasize the prognostic role of PTX3 levels and its relation to COVID-19 severity." (PMID 34680053, 2021). "The purpose of this study is to evaluate serum pentraxin-3 (PTX-3) levels in Sars-CoV-2 virus infection (COVID-19) patients and to investigate whether PTX-3 predicts the disease prognosis." (PMID 33315349, 2021). "Additionally, PTX3 has been identified as a low-cost/low-tech early biomarker for detecting secondary bacterial or fungal infections in COVID-19 patients, aiding in identification of individuals at high risk for community- or hospital-acquired infections and guiding an early antimicrobial therapy." (PMID 40313930, 2025). "Thus, our study might be considered as a validation of the predictive value of the previously identified early immune signature, extended also to PTX3, on the magnitude of protective humoral responses to COVID-19 mRNA vaccine." (PMID 39340080, 2024). "The strong correlation between PTX3 serum levels, ACE I/D polymorphism, and the MBrixia score supports the hypothesis that endothelial injury and genetic factors are important in the pathogenesis of COVID-19." (PMID 39062191, 2024). "Thus, PTX3 modulation could constitute an effective therapeutic strategy for improving the recovery from COVID-19 and its systemic long-term consequences." (PMID 37762499, 2023). "Moreover, the obtained data also indicate a degree of severity influenced by gender, as shown by the subgroup analysis, in which PTX3 expression was more pronounced in previously COVID-19-positive males (p < 0.001) than in females (p < 0.05) compared to the respective controls." (PMID 37762499, 2023). "Additionally, upregulated PTX3 was considered a predictor of COVID-19 severity." (PMID 37408184, 2023).
COVID-19 (continued). "In conclusion, our data contribute to the accumulating evidence that PTX3 blood concentration may serve as an early marker of COVID-19 severity and support the need of larger, prospective studies that would hopefully pave the way to the use of PTX3 in the routine clinical practice." (PMID 35464745, 2022). "Upregulated pentraxin 3 may be used as a potential predictor of COVID-19 severity." (PMID 34680053, 2021). "A meta-analysis identified PTX3 as a reliable marker for poor outcomes following COVID-19 infection, and it was found to be a useful clinical biomarker for predicting the 30-day risk of respiratory failure and mortality in COVID-19 patients, regardless of remdesivir or dexamethasone treatment." (PMID 41479916, 2025). "PTX3 was found to bind the SARS-CoV-2 N protein; therefore, this innate immunity molecule can probably exert resistance to COVID-19 and partially inhibit its pathogenesis." (PMID 37408184, 2023). "Most importantly, high plasma levels of PTX3, MCP1, and TNFα in COVID-19 patients have been described as early molecular indicators of adverse disease progression needing intensive care." (PMID 33399033, 2021). "We analyzed the relationships between PTX3, FGF-21, fetuin-A, and irisin levels and COVID-19 severity, concomitant metabolic abnormalities, and liver injuries." (PMID 34680053, 2021). "These genes were used as identifiers to classify the 126 patients based on the random forest algorithm, revealing that CD38, PTX3, and HSPA1A were able to classify patients into the correct groups and contribute specifically to COVID-19." (PMID 34899651, 2021). "Serum PTX3 levels were highest in intensive care unit (ICU)-admitted COVID-19 patients compared to non-ICU patients and healthy controls, suggesting a link to disease severity." (PMID 41479916, 2025). "From our research, we found increased PTX3 levels compared to healthy subjects, and notably, PTX3 was even more augmented in severe COVID-19 rather than non-severe cases." (PMID 36834949, 2023). "Additionally, receiver operator characteristic (ROC) curves demonstrated that PTX3 had higher accuracy than CRP, lactate dehydrogenase (LD), or ferritin in identifying ICU necessity during COVID-19." (PMID 37408184, 2023). "The results showed that the ICU and non-ICU COVID-19 individuals had significantly higher PTX3 levels than the controls and that PTX3 was higher among ICU-admitted patients in contrast with non-ICU but without significance." (PMID 37408184, 2023). "In the present study, the obtained data revealed a higher expression of PTX3 in previously infected COVID-19 individuals compared to never-infected subjects, confirming the potential key role of this protein in driving the immune-inflammatory process." (PMID 37762499, 2023). "We found high significative PTX3-related death in ICU COVID-19 hospitalized individuals (184 out of 543) compared to non-ICU (37 out of 515), with an overall effect OR: 11.30 [2.00, 63.73]; p = 0.006." (PMID 36834949, 2023). "The sample of COVID-19 patients comprised survivors and non-survivors, and the results showed that among non-survivors, PTX3 serum concentrations were significantly higher." (PMID 37408184, 2023). "The strongest evidence in our work is represented by the very high PTX3 serum concentration in ICU-transferred patients compared to non-ICU (median 35.86 vs 10.61 ng/mL), which suggests that PTX3 can be considered a marker of COVID-19 severity." (PMID 35464745, 2022). "The serum concentrations of sFlt-1 was significantly higher in COVID-19 patients as compared to healthy individuals; however, we did not observe significant differences in serum galectin-3 and PTX-3." (PMID 34439802, 2021). "COVID-19 patients admitted to ICU presented higher PTX3 and lower fetuin-A concentration than patients not requiring hospitalization." (PMID 34680053, 2021). "COVID-19 patients with higher ferritin levels showed increased FGF-21 and PTX3 concentrations." (PMID 34680053, 2021).